DGCR11 (DiGeorge syndrome critical region gene 11)
Synonyms: DGS-D
Gene: Long non-coding RNA gene on chromosome 22 (19,046,162 to 19,048,375, reverse strand). Ensembl gene ENSG00000273311.
Diseases named in the same sentence as DGCR11 in open-access papers:
DGCR11 is named in the same sentence as 1 disease in open-access papers, as found by Europe PMC text mining. Sharing a sentence is not in itself a finding about the gene and the disease.
DGCR11 shares sentences with these, for which no sentence is quoted: pancreatic carcinoma (1 paper).